ESR1 (estrogen receptor 1)
Description:
Nuclear hormone receptor. The steroid hormones and their receptors are involved in the regulation of eukaryotic gene expression and affect cellular proliferation and differentiation in target tissues. Ligand-dependent nuclear transactivation involves either direct homodimer binding to a palindromic estrogen response element (ERE) sequence or association with other DNA-binding transcription factors, such as AP-1/c-Jun, c-Fos, ATF-2, Sp1 and Sp3, to mediate ERE-independent signaling. Ligand binding induces a conformational change allowing subsequent or combinatorial association with multiprotein coactivator complexes through LXXLL motifs of their respective components. Mutual transrepression occurs between the estrogen receptor (ER) and NF-kappa-B in a cell-type specific manner. Decreases NF-kappa-B DNA-binding activity and inhibits NF-kappa-B-mediated transcription from the IL6 promoter and displace RELA/p65 and associated coregulators from the promoter. Recruited to the NF-kappa-B response element of the CCL2 and IL8 promoters and can displace CREBBP. Present with NF-kappa-B components RELA/p65 and NFKB1/p50 on ERE sequences. Can also act synergistically with NF-kappa-B to activate transcription involving respective recruitment adjacent response elements; the function involves CREBBP. Can activate the transcriptional activity of TFF1. Also mediates membrane-initiated estrogen signaling involving various kinase cascades. Essential for MTA1-mediated transcriptional regulation of BRCA1 and BCAS3. Maintains neuronal survival in response to ischemic reperfusion injury when in the presence of circulating estradiol (17-beta-estradiol/E2) (By similarity). [Isoform 3]: Involved in activation of NOS3 and endothelial nitric oxide production. Isoforms lacking one or several functional domains are thought to modulate transcriptional activity by competitive ligand or DNA binding and/or heterodimerization with the full-length receptor. Binds to ERE and inhibits isoform 1.
Synonyms: ER; ESR; NR3A1; Era; ER-alpha; ESRA; ESTRR
Tractability: Small molecule: an approved drug acts on it; a structure with a bound ligand is known; a high-quality ligand is known; it has a high-quality binding pocket; it belongs to a druggable protein family. Antibody: UniProt places it where antibodies can reach, with high confidence; its Gene Ontology location is reachable by antibodies, with high confidence. PROTAC: a drug acting on it is in phase 2 or 3 trials; it is named in the literature on targeted protein degradation; UniProt records ubiquitination sites on it; ubiquitination databases record sites on it; a small molecule that binds it is known. Other modalities: an approved drug acts on it.
Target class: Nuclear hormone receptor subfamily 3 group A member 1; Nuclear receptor; Nuclear hormone receptor subfamily 3 group A; Nuclear hormone receptor subfamily 3; Transcription factor
Chemical probes: AZD-9496 (high quality), CAMIZESTRANT (high quality), Compound 18, Compound 4-D, ERD-308 (high quality), ESTRADIOL BENZOATE, GDC-0810, PD080748, PD080750, PD080845, PD080899, PD080911, PD080913, PD080923, PD080965, PD081083, PD081137, PD081145, PD081247, PD081353, and 74 more
Safety:
Unwanted effects reported when the protein is acted on. In parentheses: how it was acted on, where the effect was seen, and who reports it.
Decrease, Population growth rate (AOP-Wiki: inhibition; AOP-Wiki: activation)
Altered, Larval development (activation; source: AOP-Wiki)
Altered, Reproductive behaviour (activation; source: AOP-Wiki)
breast atrophy (inhibition; reproductive; source: Brennan et al. (2024))
breast tissue growth in males (activation; reproductive; source: Brennan et al. (2024))
Hot flashes (inhibition; source: Brennan et al. (2024))
impacts sexual development (inhibition; reproductive; source: Brennan et al. (2024))
Impaired development of, Reproductive organs (activation; source: AOP-Wiki)
Increase, Endometrial adenocarcinomas (activation; source: AOP-Wiki)
Increased risk of thrombosis (activation; cardiovascular; source: Brennan et al. (2024))
Increased, adenosquamous carcinomas of endometrium (activation; source: AOP-Wiki)
irregular menstruation in females (activation; reproductive; source: Brennan et al. (2024))
N/A, Breast Cancer (activation; source: AOP-Wiki)
osteoporosis (inhibition; bone; source: Brennan et al. (2024))
Promotion, ovarian adenomas (inhibition; hypothalamus; source: AOP-Wiki)
Promotion, ovarian granular cell tumors (inhibition; hypothalamus; source: AOP-Wiki)
skewed, sex ratio (activation; source: AOP-Wiki)
vaginal atrophy (inhibition; reproductive; source: Brennan et al. (2024))
azoospermia (source: ClinPGx)
bone density loss (source: ClinPGx)
bone mineral density loss (source: ClinPGx)
bone mineral loss (source: ClinPGx)
decrease in high density lipoprotein (source: ClinPGx)
decrease in total cholesterol (source: ClinPGx)
Decreased sperm quantity / quality in the adult, Decreased fertility (source: AOP-Wiki)
larger tamoxifen-induced decrease in total cholesterol (source: ClinPGx)
less bone mineral loss (source: ClinPGx)
methamphetamine-induced psychosis (source: ClinPGx)
musculoskeletal pain (source: ClinPGx)
tamoxifen-induced decrease in total cholesterol (source: ClinPGx)
and 1 more effect
Gene: Protein-coding gene on chromosome 6 (151,651,284 to 152,129,619, forward strand). Ensembl gene ENSG00000091831.
Subcellular location: Nucleus (Isoform 1); Cytoplasm; Cell membrane; Nucleus (Isoform 3); Nucleus; Golgi apparatus
Subcellular location (Human Protein Atlas): Vesicles; Nucleoplasm
Pathways (Reactome):
Signal Transduction: ESR-mediated signaling; Estrogen-dependent gene expression; Extra-nuclear estrogen signaling; Nuclear signaling by ERBB4; PI5P, PP2A and IER3 Regulate PI3K/AKT Signaling; PIP3 activates AKT signaling
Gene expression (Transcription): Nuclear Receptor transcription pathway; RUNX1 regulates estrogen receptor mediated transcription; RUNX1 regulates transcription of genes involved in WNT signaling; Regulation of RUNX2 expression and activity; TFAP2 (AP-2) family regulates transcription of growth factors and their receptors
Developmental Biology: Developmental Lineage of Mammary Gland Alveolar Cells; Developmental Lineage of Mammary Gland Luminal Epithelial Cells
Metabolism of proteins: Ovarian tumor domain proteases; SUMOylation of intracellular receptors
Cellular responses to stimuli: Mitochondrial unfolded protein response (UPRmt)
Disease: Constitutive Signaling by Aberrant PI3K in Cancer
Gene Ontology:
Molecular function: 14-3-3 protein binding; ATPase binding; beta-catenin binding; calmodulin binding; chromatin binding; DNA-binding transcription activator activity, RNA polymerase II-specific; enzyme binding; estrogen response element binding; identical protein binding; nuclear estrogen receptor activity; nuclear estrogen receptor binding; nuclear receptor activity; protein binding; protein kinase binding; RNA polymerase II cis-regulatory region sequence-specific DNA binding; sequence-specific double-stranded DNA binding; TBP-class protein binding; TFIIB-class transcription factor binding; transcription coactivator binding; transcription coregulator binding; transcription corepressor binding; DNA-binding transcription factor activity; DNA-binding transcription factor activity, RNA polymerase II-specific; nitric-oxide synthase regulator activity; steroid binding; and 4 more
Biological process: cellular response to estradiol stimulus; estrogen receptor signaling pathway; negative regulation of canonical NF-kappaB signal transduction; negative regulation of gene expression; negative regulation of miRNA transcription; negative regulation of transcription by RNA polymerase II; positive regulation of DNA-templated transcription; positive regulation of transcription by RNA polymerase II; protein localization to chromatin; response to estradiol; response to estrogen; RNA polymerase II preinitiation complex assembly; cellular response to estrogen stimulus; chromatin remodeling; negative regulation of smooth muscle cell apoptotic process; nuclear receptor-mediated steroid hormone signaling pathway; phospholipase C-activating G protein-coupled receptor signaling pathway; positive regulation of cytosolic calcium ion concentration; regulation of DNA-templated transcription; regulation of transcription by RNA polymerase II; signal transduction; stem cell differentiation; steroid hormone receptor signaling pathway
Cellular component: chromatin; cytoplasm; euchromatin; nucleus; plasma membrane; protein-containing complex; transcription regulator complex; cytosol; membrane; nucleoplasm; Golgi apparatus
Genetic constraint (gnomAD): Loss-of-function variants: 15 observed, 50.66 expected, observed/expected ratio (o/e) 0.3, 90% interval 0.2 to 0.46. The upper end of that interval is the gene's LOEUF score, 0.46, which puts it in group 2 of 6, group 1 being the genes least tolerant of losing a copy. Missense variants: 557 observed, 740.33 expected, observed/expected ratio (o/e) 0.75, 90% interval 0.7 to 0.81. Synonymous variants: 297 observed, 303.9 expected, observed/expected ratio (o/e) 0.98, 90% interval 0.89 to 1.08.
Cancer hallmarks: invasion and metastasis (promotes); proliferative signalling (promotes); suppression of growth (promotes); invasion and metastasis (suppresses); escaping immune response to cancer (promotes)
Homologues: Orthologues: chimpanzee ESR1 (99% identical), macaque ESR1 (99% identical), pig ESR1 (92% identical), rabbit ESR1 (91% identical), dog ESR1 (90% identical), mouse Esr1 (90% identical), rat Esr1 (89% identical), guinea pig ESR1 (86% identical), tropical clawed frog esr1 (70% identical), zebrafish esr1 (46% identical), Drosophila melanogaster ERR (21% identical). Paralogues in human: ESR2 (40% identical), ESRRG (27% identical), ESRRB (26% identical), ESRRA (24% identical), PGR (22% identical), NR3C1 (21% identical), AR (21% identical), NR3C2 (20% identical).
Diseases named in the same sentence as ESR1 in open-access papers:
ESR1 is named in the same sentence as 866 diseases in open-access papers, as found by Europe PMC text mining. Sharing a sentence is not in itself a finding about the gene and the disease. The quoted sentences say what the papers report.
breast cancer (12,242 papers, 1993 to 2026). A primary or metastatic malignant neoplasm involving the breast. "Breast cancer is characterised by profound genetic heterogeneity, with oestrogen receptor alpha (ERα, encoded by ESR1) being a central driver in ~70% of cases." (PMID 42135449, 2026). "ESR1 is a widely used diagnostic marker in breast cancer pathology, and several anti-human ESR1 antibodies have been developed for this purpose." (PMID 41543558, 2026). "Patients with estrogen receptor+ (ER+, ESR1+) breast cancer are most at risk of relapse, where activating mutations in ESR1 promote metastasis and therapeutic resistance." (PMID 41797713, 2026). "Endocrine therapy (ET) resistance in estrogen receptor positive (ER+) advanced breast cancer is often linked to ESR1 mutations, yet responses to oral selective ER degraders vary within mutant subgroups." (PMID 41820395, 2026). "ESR1 mutations account for a common factor affecting ESR1 transcription in breast cancer, which predominantly occur in patients with HR+ breast cancer who have undergone a period of aromatase inhibitor (AI) treatment." (PMID 41357671, 2025). "AC682 is a chimeric compound that, given alone or plus CDK4/6is or PI3K/mTOR pathway inhibitors, showed anticancer activity in experimental ER+ breast cancer models, including those with ESR1 mutations." (PMID 40244377, 2025). "In uterine endometrioid carcinomas, we identified ESR1 activating mutations in two patients at amino acid residue 537 resulting in a mutation hotspot commonly seen in patients with breast cancer who have become resistant to estrogen-targeted therapies." (PMID 40981433, 2025). "Approximately 40% of breast cancer patients develop resistance to endocrine therapy, with ESR1 mutations being a common mechanism of acquired resistance." (PMID 40299687, 2025). "Conversely, functional variants of miRNA target sites in several genes, including the ESR1 gene, have been identified, where the rs2747648 SNP modifies miR-453 binding, thereby affecting breast cancer risk." (PMID 41153361, 2025). "Liquid biopsy-based ESR1 mutation detection represents a pivotal advance in precision oncology for breast cancer, enabling personalized management and improved patient outcomes." (PMID 41142848, 2025). "Specific cases, such as treatments targeting the ESR1 mutation in breast cancer, MSI and TMB-high in biliary tract cancer, and CDK12 mutation in head and neck cancer—detected exclusively through ctDNA but not in tissue samples—demonstrated partial responses." (PMID 40209142, 2025). "ZFHX3 loss promotes ESR1-mediated cell proliferation in ESR1-positive breast cancer cells by upregulating breast cancer stem cells and MYC transcription, and similar findings have been reported in androgen receptor-positive prostate cancer." (PMID 41413856, 2025). "As hormone receptor status is a critical driver of treatment in breast cancer, mutations in ESR1 that lead to hormone resistance play a substantial role in determining treatment algorithm and overall outcome." (PMID 40647516, 2025). "Our study highlights liquid biopsy as a preferred approach for monitoring ESR1 mutations in breast cancer patients by showing cases where NGS analysis suggests complex tumor heterogeneity with multiple ESR1 as well as PIK3CA mutations at different VAFs." (PMID 40282442, 2025). "In breast cancer, we observed that the lead variants were significantly enriched in the TFs ESR1 (n = 73 genes), followed by TCF7L2 (n = 13) and FOXA1 (n = 11) (Fisher’s exact test, P < 0.01 for all)." (PMID 39535029, 2025). "This indicates that fulvestrant remains an effective treatment option for breast cancer patients with ESR1 mutations alone." (PMID 41357671, 2025). "Our database identified well-known fusion genes that are commonly associated with breast cancer, such as ESR1::CCDC170, and revealed previously unreported fusion genes, including TPTE2::MRPS31P2 and LHFPL5::CLPSL1." (PMID 41213951, 2025).
breast cancer (continued). "Resistance mutations in the ESR1 gene occur commonly in breast cancer patients previously treated with anti-hormonal therapy." (PMID 40282442, 2025). "With regard to HDAC proteins, it is widely documented that HDAC inhibitors inhibit E2 signaling in breast cancer cells by inducing transcriptional repression of ESR1, the ERα-encoding gene, as well as ERα protein degradation." (PMID 40479062, 2025). "In one study, the effectiveness of CDK4/6is in relapsed breast cancer with ESR1 mutations (ESR1m) was assessed using circulating tumor DNA (ctDNA) analysis." (PMID 40244377, 2025). "For instance, in breast cancer, ESR1 mutation detection by ctDNA led to an ORR of 25% (n = 4) with SERD therapy, whereas in ovarian cancer, DNA damage repair gene mutation detection resulted in an ORR of 0% (n = 2) with PARP inhibitors." (PMID 40209142, 2025). "In order to develop an ESR1 resistance mutation assay for use in breast cancer patients, we wanted to understand how frequently ESR1 mutations occur in a pan-cancer cohort without prior ET." (PMID 40282442, 2025). "Breast cancer (BC) is a multifactorial condition and it primarily expresses the estrogen receptor α (ERα) that is encoded by the gene estrogen receptor 1 (ESR1), which modulates estrogen signaling." (PMID 40243758, 2025). "Models of endocrine therapy resistance are reported to have elevated JNK activity, suggesting that JNK signalling is oncogenic in this setting, and that JNK is activated in ER+ breast cancer cells with ESR1 mutation." (PMID 40826108, 2025). "In this first-in-human phase 1/2 study, palazestrant demonstrated a manageable safety profile with antitumor activity observed in heavily pretreated patients with both wild-type and ESR1-mutated breast cancer." (PMID 40598566, 2025). "This concept parallels estrogen receptor 1 (ESR1) mutations in HR-positive breast cancer, in which approximately 20% of patients develop acquired mutations following endocrine therapy, whereas 1–5% harbor de novo ESR1 mutations at baseline." (PMID 40566067, 2025). "High CBLL1 gene expression was associated with a better prognosis in patients with breast cancer, and functional analysis revealed its involvement in the regulation of multiple pathways, including apoptosis, the ESR1-pathway, and immune response." (PMID 39833727, 2025). "Genes central to the main female-biased cancers (melanoma, gastric and thyroid), breast cancer and ESR1, which encodes oestrogen receptor-α (ERα), include CDH1 (which encodes E-cadherin), CCND1 (cyclin D1), BRAF and KRAS." (PMID 40500450, 2025). "Further, when HR+/HER2- breast cancer patients progress on endocrine therapy due to emergence of ESR1 resistance mutations, elacestrant therapy can significantly prolong PFS." (PMID 40711866, 2025). "BRCA1 and ESR1 gene mutations specifically cause breast cancer, while error in the CYP19A gene leads to cancers in the endometrium, ovaries, and thyroid." (PMID 41514592, 2025). "A study utilizing a blood-based molecular test with high sensitivity and specificity to identify ESR1 alterations in CTCs and ctDNA from individuals with breast cancer revealed discordance in ESR1 mutation results." (PMID 40108089, 2025). "Another important field of adoption of ctDNA analysis in breast cancer patients is for the identification of ESR1 resistance mutations in ER‐positive, HER2‐negative breast cancer patients after endocrine therapy, with a digital droplet PCR (ddPCR) approach." (PMID 40219616, 2025). "A longitudinal analysis of breast cancer patients showed distinct ESR1 mutated clones that exhibited divergent behavior over time, strongly suggesting clonal heterogeneity." (PMID 40282442, 2025). "Large-scale genomic studies, such as The Cancer Genome Atlas (TCGA) project, have provided critical insights into the genomic landscape and heterogeneity of breast cancer, revealing a higher frequency of ESR1 mutations in MBC." (PMID 40641933, 2025).